AR (androgen receptor)
Diseases named in the same sentence as AR in open-access papers (continued):
Sharing a sentence is not in itself a finding about the gene and the disease.
prostate carcinoma (continued). "For example, androgen receptor splice variant 7 (AR-V7) was correlated with resistance to hormonal therapy in patients with castration-resistant prostate cancer." (PMID 36674900, 2023). "The purpose of our work was to explore the association of mutations in the androgen receptor gene and copy numbers of the androgen-receptor silk protein A complex with glutathione-S-transferases T1 and M1 in prostate cancer patients." (PMID 36824501, 2023). "AR is a ligand-dependent transcription factor that regulates the specific genes associated with prostate cancer growth and metastasis." (PMID 37375297, 2023). "Androgen receptor has a critical role in regulating the growth and differentiation of prostate cells and is frequently overexpressed or mutated in prostate cancer cells." (PMID 37104249, 2023). "This is particularly important in prostate cancer where aberrant RNA splicing, particularly of the androgen receptor, is associated with therapy resistance and poor prognosis." (PMID 37509260, 2023). "Androgen receptors (ARs) are the hallmark therapeutic target for prostate cancer modulation and AR antagonists have achieved great success." (PMID 37149650, 2023). "Restored AR activity in enzalutamide refractory prostate cancer cells is associated with reduced LCMT1." (PMID 37644036, 2023). "Development and progression of prostate cancer has been linked to a complicated array of interacting signal transduction cascades including androgen receptor (AR) signalling, cyclic AMP (cAMP)/protein kinase A (PKA) signalling and Wnt signalling." (PMID 37830741, 2023). "In prostate cancer (PCa), the ncRNAs have been reported to be associated with AR expression, PCa proliferation, and castration resistance." (PMID 37644825, 2023). "The LNCaP prostate cancer cell line contains a T877A point mutation in the ligand-binding domain of the androgen receptor which converts hydroxyflutamide into an agonist." (PMID 38131032, 2023). "Therapy-induced neuroendocrine prostate cancer (NEPC) is a highly lethal variant of prostate cancer that is increasing in incidence with the increased use of next-generation of androgen receptor (AR) pathway inhibitors." (PMID 36711033, 2023). "Recent findings have highlighted translation initiation as a critical driver in AR-deficient prostate cancer, wherein the AR negatively regulates protein synthesis through transcriptional control of 4EBP18." (PMID 37646236, 2023). "Neuroendocrine prostate cancer (NEPC) is a lethal form of prostate cancer characterized by loss of AR expression and thus resist ADT." (PMID 36727462, 2023). "As reported in various studies, androgen receptor (AR) has been increasingly implicated in prostate cancer." (PMID 36937425, 2023). "This is accompanied by an increase in the ratio of androgen receptor‐FL to truncated androgen receptor variants, presenting a promising therapeutic target for manipulating androgen signalling in patients with prostate cancer." (PMID 37850412, 2023). "AR inhibition has been shown to cause DNA damage on telomeres to prostate cancer cells in previous literature, so we evaluated our drug combinations in DNA synthesis, DNA damage, and apoptosis." (PMID 37456235, 2023). "In future studies, we will continue to collect androgen-receptor gene mutations in prostate cancer patients, aiming to conduct multicenter studies to improve the representativeness of the results of this study." (PMID 36824501, 2023). "For example, lncRNA ARLNC1 interacts with mRNA encoding the androgen receptor (AR) to induce oncogenic AR signal transduction, proliferation, and survival; it further participates in the occurrence and progression of prostate cancer." (PMID 36793272, 2023). "In prostate cancer patients, low serum testosterone has been found to be associated with androgen receptor expression." (PMID 37384143, 2023). "The role of the 4EBP-eIF4E axis in AR-deficient prostate cancer presents intriguing opportunities for therapeutic intervention." (PMID 37646236, 2023).
prostate carcinoma (continued). "For instance, Androgen receptor splice variant 7 (ARV7) is associated with abiraterone resistance in castration-resistant prostate cancer." (PMID 37215575, 2023). "Rb loss and E2F1 activation increase AR levels in prostate cancer and are associated with CRPC, in which the AR can promote cell growth and proliferation in a hormone-independent fashion." (PMID 37363926, 2023). "The ROS-inducing effects of androgens are associated with AR-induced metabolism and activation of pro-oxidative signaling pathways which stimulate prostate cancer cell growth and proliferation." (PMID 37874216, 2023). "In this study, genomic activities of wild‐type AR (AR‐WT) were compared with those of AR‐Q641X and AR‐V7, two constitutively active AR variants that are associated with castration‐resistant prostate cancer." (PMID 34919781, 2022). "AR expression in epithelial cells is thought to cause prostate cancer, and this cell type’s role in the development of the disease is significant." (PMID 36142861, 2022). "Is statin use during androgen-ablative therapies (androgen deprivation or androgen receptor axis–targeted therapies) associated with reduced mortality among men with prostate cancer?" (PMID 36449294, 2022). "Overcoming challenges of determining gene amplification from liquid biopsies, these assays cross-validate each other to produce reliable AR amplification and mutation data from plasma cell free DNA (cfDNA) of advanced prostate cancer (PC) patients." (PMID 35011998, 2022). "Castration resistance is a lethal form of treatment failure of prostate cancer (PCa) and is associated with ligand-independent activation of the androgen receptor (AR)." (PMID 35365763, 2022). "Therapy-induced neuroendocrine prostate cancer (t-NEPC/NEPC) is an aggressive variant of prostate cancer (PCa) that frequently emerges in castration-resistant prostate cancer (CRPC) under the selective pressure of androgen receptor (AR)-targeted therapies." (PMID 35447888, 2022). "The development of prostate cancer is attributable to a mutation in the androgen receptor (AR), which is fundamental in the genetic expression of many tissues, including the prostate." (PMID 36421730, 2022). "Paracrine FGF10 signaling to prostate cancer cells causes increased AR expression and activated AKT." (PMID 36671452, 2022). "Increased ROS production in prostate cancer cells results in oxidative stress and associated metabolic alterations, androgen receptor activation and mutation-induced dysfunction of mitochondria." (PMID 35158943, 2022). "For instance, downregulation of TET2 has been implicated in the regulation of AR signalling and prostate cancer development." (PMID 35205419, 2022). "The AR-V7/AR3 variant of AR can be activated independently of its ligand, as described in prostate cancer cells, and its occurrence has been confirmed in GBM." (PMID 36361793, 2022). "In a 2018 study, researchers developed three different prostate cancer (PC) PDX models characterized by different androgen receptor (AR) expression and breast cancer associated two (BRCA2) status (wild type versus mutated)." (PMID 35466279, 2022). "Unique gene transcription programs modulated by the AR or particular splice variants have been reported and there was limited overlap between the two prostate cancer cell lines expressing different AR variants." (PMID 35682963, 2022). "Given the close association between AR and GR, GR has been suggested to play a role in enzalutamide resistance in prostate cancer." (PMID 35866830, 2022). "Treatment-emergent neuroendocrine prostate cancer (NEPC) after androgen receptor (AR) targeted therapies is an aggressive variant of prostate cancer with an unfavorable prognosis." (PMID 36159187, 2022). "H3K27 acetylation and H3K9 methylation have been linked to AS of the human Ar gene, coding for the Androgen Receptor, which plays pivotal roles in prostate cancer (PC), especially castration-resistant prostate cancer (CRPC)." (PMID 35955433, 2022).
prostate carcinoma (continued). "Plenty of attention has been paid to AR gene polymorphisms, especially poly Q and poly G, which are related to prostate cancer, breast cancer, lung cancer, etc.." (PMID 35886904, 2022). "miR-346 was identified as an activator of Androgen Receptor (AR) signalling that associates with DNA damage response (DDR)-linked transcripts in prostate cancer (PC)." (PMID 35317841, 2022). "The A031 PROTAC caused AR degradation in VCaP prostate cancer cells that contain a high copy number genomic AR." (PMID 35205640, 2022). "Expression of the AR splice variant, androgen receptor variant 7 (AR-V7), in prostate cancer is correlated with poor patient survival and resistance to AR targeted therapies and taxanes." (PMID 35848798, 2022). "Prostate cancer is driven by the androgen receptor, and is directly associated with nuclear steroidal AR." (PMID 36405317, 2022). "Our results indicate that ivermectin inhibited dramatically prostate cancer in cell lines representing the hormone-sensitive stage (LNCaP), castration resistance stage (C4-2), and AR variant positive stage (22RV1)." (PMID 36050295, 2022). "During ADT, prostate cancer cells can regulate AR activity through AR gene amplifications, mutations, and post-translational modifications to adapt to the chronic androgen deprivation environment." (PMID 37113653, 2022). "Prostate cancer (PCa) is a leading cause of cancer-related deaths and is driven by aberrant androgen receptor (AR) signalling." (PMID 36291932, 2022). "We conclude that both FKBPs promote dimer formation in AR and activate AR‐dependent transcription, which is associated with the etiology of prostate cancer." (PMID 34057812, 2022). "Capsaicin induces autophagy blockage and apoptosis in prostate cancer PC-3 cells, inhibits the growth of castration-resistant prostate cancer cells and causes the degradation of the androgen receptor (AR)." (PMID 35214061, 2022). "A better understanding of the rules governing AR activation is of great importance, as multiple pathologies are associated with aberrant AR transcriptional output, including prostate cancer and androgen insensitivity syndrome (AIS)." (PMID 35447082, 2022). "A splice variant of the androgen receptor that drives prostate cancer resistance translocates into the nucleus using a different mechanism from the full-length receptor and exhibits distinct molecular properties once inside." (PMID 35998026, 2022). "Men with higher androgen receptor transcriptional activity have a higher risk of TMPRSS2-ERG fusion-positive prostate cancer." (PMID 35017320, 2022). "A cross analysis with primary prostate cancer samples was performed, finding AR and GN17AS mutations to arise exclusively in mCRPC patients." (PMID 36551557, 2022). "Modulated DNA repair gene expression in the presence of AR splice variants is linked to increased DNA repair activity, pointing at a novel therapeutic approach for castration-resistant prostate cancer." (PMID 36139600, 2022). "The CRIPSCs also expressed prostate stem cell antigen (Psca) and cyclin-dependent kinase 6 (Cdk6); the latter can associate with AR and enhance its transcriptional activity in prostate cancer cells." (PMID 35841025, 2022). "According to the GSVA analysis, apoptosis, cell cycle, DNA damage, epithelial-mesenchymal transition (EMT), androgen receptor (hormone AR) pathways, among others, were associated with the hub genes in prostate cancer." (PMID 36245843, 2022). "Another aspect involved in AR signaling and considered a risk factor for the development and aggressiveness of human prostate cancer refers to the number of polyglutamine (polyQ) repeats in the N-terminal transactivation domain of the AR gene." (PMID 35681707, 2022). "The implication of AR has drawn comparisons with prostate cancer and therein the potential role of AR splice variants as well as pioneering transcriptional regulatory roles." (PMID 35734391, 2022).
prostate carcinoma (continued). "We found that PC3 and DU145 prostate cancer cells that are naturally deficient in AR activity express high levels of TRIB2 protein." (PMID 34973338, 2022). "At a molecular level, hypoxia can potentiate AR gene and protein expression, including modulation of both the full-length and variant AR, in a prostate cancer cell specific manner." (PMID 35302608, 2022). "In a systemic study, exome sequencing of 150 metastatic CRPC biopsy specimens demonstrated 63% of AR mutation and amplification in comparison to 440 primary prostate cancer tissues." (PMID 35800367, 2022). "BPH, androgenic alopecia, and prostate cancer are associated with high levels of DHT produced by SRD5A2 because of excessive AR signaling." (PMID 36344974, 2022). "We also found that rs6152 at position ChrX:66,765,627 forms a contact with a chromatin fragment containing an active enhancer 2,765,787 associated with prostate cancer at a p-value of 1.6 × 10− 2 and affecting the expression of AR." (PMID 35176995, 2022). "The crucial role of AR in the development and progression of prostate cancer has been acknowledged, and the expression of AR in susceptible male individuals, such as RCC and melanoma, has also been reported." (PMID 35452181, 2022). "BRD2 overexpression in cooperation with BRD4 causes chromatin decompaction and androgen receptor activation, which lead to prostate cancer development." (PMID 35401196, 2022). "CTCs isolated from prostate cancer patients can express PSA and show molecular characteristics of prostate cancer such as AR copy number gain, PTEN loss and TMPRSS2-ETS gene fusion." (PMID 35715640, 2022). "Collectively, over 150 mutations have been reported by the Androgen Receptor Gene Mutations Database within the LBD domain of AR in the context of prostate cancer, including single point mutations, pre-termination, deletions, and insertions." (PMID 35864113, 2022). "NEPC is an aggressive variant of prostate cancer that exhibits not only AR independence but also neuroendocrine (NE) differentiation and even distinct histological features such as small cell carcinoma instead of adenocarcinoma." (PMID 35582526, 2022). "While many of these sites are not normally associated with active transcription, the overexpression of AR cofactors in prostate cancer is thought to activate expression of pro-proliferative genes at these lower affinity degenerate sites." (PMID 35447082, 2022). "We determine that an active MYC transcriptional program and low AR activity identify prostate cancer patients predisposed to fail standard-of-care therapies and most likely to develop metastatic castration resistant prostate cancer (mCRPC)." (PMID 35562350, 2022). "Reprogramming of the AR cistrome and subsequent alterations in AR-dependent gene expression underly prostate cancer progression." (PMID 36212399, 2022). "Deregulated mRNA translation rates have previously been implicated in aberrant gene expression and aggressive AR-low prostate cancer in the Ptenfl/fl mouse." (PMID 36511483, 2022). "In other words, ADT-refractory prostate cancer remains androgen-driven, probably due to activating AR mutations or amplifications that result in increased protein expression." (PMID 36551557, 2022). "NE differentiation in prostate cancer is associated with a more aggressive phenotype, metastatic disease, and poor response to AR signaling inhibitors." (PMID 35582526, 2022). "AR is the single most important regulatory mechanism in prostate cancer and its functional loss leads to CRPC onset." (PMID 36142477, 2022). "If this is important in its biological effects on reproductive, musculoskeletal and hemopoietic systems, it is crucial in prostate cancer, as AR variants influence the efficacy and prognosis of androgen deprivation therapy (ADT)." (PMID 35408895, 2022). "Modulation of AR signaling underlies prostate cancer progression and can be partly attributed to the reprogramming of the AR cistrome during prostate tissue transformation." (PMID 36212399, 2022).
prostate carcinoma (continued). "We conclude that FKBP51 and FKBP52 promote dimer formation of AR and activate AR‐dependent transcription, which is associated with the etiology of prostate cancer." (PMID 34057812, 2022). "This further affirms our cytological and biochemical data wherein VNPP433-3β was shown to directly engage AR in live cells of prostate cancer and mediates proteasome-dependent degradation of full-length AR and the clinically significant splice variant AR-V7." (PMID 36078112, 2022). "HNRNPL directly regulates the AS of various RNAs, including those encoding the AR as well as the key lineage-specific prostate cancer oncogene." (PMID 36052164, 2022). "For instance, we have qualified and analytically validated CTC assays for androgen receptor (AR), AR splice variant 7, and synaptophysin (prostate cancer), HER2 and ER (breast cancer), and PD-L1 (immune-oncology)." (PMID 35308236, 2022). "This is consistent with a growing appreciation of the highly aggressive role of neuroendocrine differentiation with gradual loss of AR in prostate cancer progression." (PMID 36033483, 2022). "In the vast majority of cases, resistance to ADT is mediated by adaptive alterations to the AR signaling axis, highlighting addiction to this pathway as a hallmark of prostate cancer." (PMID 36923279, 2022). "Knocking down MYC in various human prostate cancer cell lines led to decreased expression of full-length AR and its splice variants, along with decreased expression of their target genes." (PMID 36212399, 2022). "We find that inhibiting PKCβ reduces total AR transcript levels, including AR-V7 splice variant levels, and sensitizes AR-V7-positive prostate cancer cells to existing anti-androgen therapies." (PMID 35087237, 2022). "Dysregulation of alternative splicing in prostate cancer is linked to transcriptional programs activated by AR, ERG, FOXA1, and MYC." (PMID 36170835, 2022). "AR regulates the expression of the DNA damage repair genes, AR chromatin binding sites are highly mutated in prostate cancer cells, and activation of AR promotes generation of fusion genes." (PMID 35164752, 2022). "The AR p.H875Y mutation has been predominantly found in prostate cancer, but this mutation has also been reported for breast cancer and CRC." (PMID 35053623, 2022). "Dysregulation of Androgen Receptor (AR) signaling is the major pathway associated with prostate cancer (PCa) progression, and agents targeting AR represent the mainstay of pharmacologic therapy for PCa." (PMID 35252555, 2022). "Misfolding of the AR‐NTD is implicated in prostate cancer and Kennedy's disease, yet our knowledge of its structure is limited to primary sequence information of the chain and a few functionally important secondary structure motifs." (PMID 35634773, 2022). "Loss- or gain-of-function of the AR contributes to pathologies such as the androgen insensitivity syndrome and prostate cancer." (PMID 35163481, 2022). "We selected the CWR22Pc-R1-AD1 prostate cancer cell line, which expresses a single copy of the AR gene with the AR H875Y mutation and is derived from the primary human prostate tumor CWR22." (PMID 36611998, 2022). "The 22RV1 prostate cancer cell line expresses full-length AR and AR-V7 splice variant and includes a drug-binding-resistant somatic mutation in the full-length AR LBD (H875Y)." (PMID 35087237, 2022). "Among the AR splice variants (AR-Vs), AR-V7 is the most abundant variant and has the highest detection frequency in prostate cancer." (PMID 35935969, 2022). "Prior studies have shown that AR variants such as ARV7 modulated the NF-κB activity in prostate carcinoma cells." (PMID 35053438, 2022). "Lineage plasticity of prostate cancer is associated with resistance to androgen receptor (AR) pathway inhibition (ARPI) and supported by a reactive tumor microenvironment." (PMID 35963852, 2022).